MYC (MYC proto-oncogene, bHLH transcription factor)
Diseases named in the same sentence as MYC in open-access papers (continued):
Sharing a sentence is not in itself a finding about the gene and the disease.
cancer (continued). "Deregulated MYC genes require co-operative lesions to foster tumourigenesis and both direct and indirect evidence support activated Ras signaling for this purpose in many cancers." (PMID 16822308, 2006). "pU27 is a G-rich tract of DNA found in the Nuclease Hypersensitive Element III1 (NHE III1) region of the c-MYC P1 promoter, and its parallel G4 structure has been linked to transcriptional repression of aberrant c-MYC expression, resulting in suppression of cancer proliferation." (PMID 41495908, 2026). "Oncogenes such as MYC, AKT1, AKT2, cyclins CCNA2, CCNB1, CCNB2, CCNE1, CCNE2 and cyclin-dependent kinases CDK1 and CDK4, which were upregulated under androgen treatment, exhibited a significantly reduced expression following PVT1 knockdown, thereby modulating cancer-associated oncogenic pathways." (PMID 41792045, 2026). "Evidence strongly proposes that MYC/mTOR-driven tumorigenic signaling can predominantly control the translational machinery to elicit cooperative effects on increased cell proliferation, cell cycle progression, and genome dysregulation as a mechanism of cancer initiation." (PMID 39779613, 2025). "However, in the last 20 years, the routine use of next-generation sequencing approaches allowed for the identification of MYC point mutations in various cancer types, including both solid and non-solid tumors, often in association with poor outcomes." (PMID 41008653, 2025). "By strategically harnessing the complementary mechanisms of MYC-targeted agents alongside conventional or immune-based therapies, oncology research stands to substantially enhance treatment effectiveness, overcome adaptive resistance, and ultimately improve patient outcomes in MYC-driven cancers." (PMID 40365020, 2025). "Future studies to further clarify the interaction of these two important transcriptional pathways in HSF1 and MYC, identify actionable therapeutic targets, and disrupt cancer-promoting pathways that could lead to clinical advances in a precision medicine therapeutic approach are warranted." (PMID 39831777, 2025). "Third, access of rLon, specifically the NTD and AAA + domains, to MYC promoters may be enhanced in the open chromatin of rapidly dividing cells in cancer or infection, possibly accounting for the pronounced transcriptional inhibition detected in diseased tissues but not in healthy tissues." (PMID 40000737, 2025). "Additionally, MYC-induced changes in cellular energetics may provide the ATP required for energy-intensive repair processes, further supporting cancer cell survival under genotoxic stress." (PMID 41561634, 2025). "Finally, we found that the cancer-related MBM vs. ECM signature genes had positive associations with five of seven previously identified principal signature gene classes of melanocytic phenotypes (Invasive, Neuro, AXL, Amelanotic, and Mitotic/MYC)." (PMID 40954493, 2025). "MYC could interact with lncRNA EPIC1 to promote cell cycle progression in cancer." (PMID 40478912, 2025). "Another major and immediate downstream effect of MYC activation is a dramatic increase in metabolism of the cells as it directly upregulates energy/ATP production rates through transcriptional and protein synthesis control to sustain the uncontrolled cancer cell proliferation." (PMID 39779613, 2025). "Multiple mechanisms could account for why MYC-driven cancer models are dependent on SUMOylation." (PMID 40487451, 2025). "Thus, we conclude that FFX potentiates MYC and augments mTOR signaling in human cancer." (PMID 40027648, 2025). "In cancer, mutations in APC or CTNNB1 (β-catenin) lead to permissive β-catenin machinery, subverting TCF/LEF transcription factors to unleash tumorigenic gene expression, including MYC, CCND1, and AXIN2, promoting unbridled proliferation, stemness, and therapeutic resistance." (PMID 40874062, 2025).
cancer (continued). "Moreover, the redundancy of MYC dosage compensation—mediated by at least three different miRNAs from the miR-17/92 cluster requires the development of specialized strategies capable of simultaneously inhibiting multiple miRNAs while ensuring selective cytotoxicity in MYC-amplified cancer cells." (PMID 40940795, 2025). "The proto-oncogene MYC is one of the most investigated genes; thanks to its central role it is defined as the “master regulator” of cellular growth and proliferation and given its significant implication in tumorigenesis, it is also considered a crucial “director” of cancer growth." (PMID 40507925, 2025). "Therefore, investigating the role of MYC in regulating ferroptosis in neutrophils across different cancers may represent a significant research gap that warrants further exploration." (PMID 40732268, 2025). "In addition, with recent advances in MYC targeting, combining MYC inhibitors with ncRNA therapeutics could provide a powerful new strategy for treating MYC-driven cancers." (PMID 40126351, 2025). "Moreover, c-MYC upregulation confers mesenchymal features in several cancers, including HCC." (PMID 40521302, 2025). "In addition, snoRA51 enhanced cancer stem cell-like properties via the RPL3/NPM1/c-MYC pathway." (PMID 41510246, 2025). "Notably, the MYC, E2F2 and CASP8 genes, which are important regulators of the cell cycle and apoptosis and have previously been implicated in HPV-related processes or cancer, were identified as common trans-interaction sites in both the HiC and 4C datasets." (PMID 40892869, 2025). "Additionally, this reprogramming supports the phenotypic plasticity of cancer cells, enabling transitions between different cellular states, for instance, in breast cancer, overexpression of MYC triggers phenotypic transitions and induces a stem cell-like state." (PMID 40032852, 2025). "Moreover, the use of cancer cell lines with varying MYC copy numbers reveals the dosage-dependence of the cytotoxicity induced by the interruption of the miR-17/92-mediated regulatory loops of MYC expression." (PMID 40940795, 2025). "Notably, MYC, SMAD3, and TGFB1 were implicated in more than four cancer hallmarks." (PMID 40149461, 2025). "Interestingly, as illustrated in the shinyDepMap plot, NAA10 and MYC display similar efficacy and selectivity scores in CRISPR and shRNA screens, further supporting a regulatory association between NAA10 and MYC in certain cancers." (PMID 40558489, 2025). "Notably, USP28 mutants found in cancer may retain the ability to stabilize MYC, thus maintaining oncogenic signaling." (PMID 41365927, 2025). "Therefore, MYC is one of the most alluring therapeutic targets for developing cancer drugs." (PMID 40290126, 2025). "Of note, the double knockdown of YY1 and MYC consistently showed low cancer scores after perturbations in the majority of cases, confirming that the combination of YY1 and MYC may exhibit synergistic effects, rendering them promising target genes for cancer reversion." (PMID 39840939, 2025). "However, the complexity of metabolic programs in cancer cells and the potential for adaptive resistance require the development of combination therapies that target MYC-driven metabolism alongside other cellular pathways such as compensatory signaling pathways and DNA repair." (PMID 39779613, 2025). "Another major and immediate downstream effect of MYC activation is a dramatic increase in metabolism of the cells as it directly regulates and increases energy/ATP production rates through transcriptional and protein synthesis control to sustain the uncontrolled cancer cell proliferation." (PMID 38200580, 2024).
cancer (continued). "Inhibition of c-MYC, on the other hand, has been observed to promote apoptosis, growth arrest, differentiation, senescence, metabolic changes, as well as tumour regression in several human cancer models, clearly indicating its potential as a target for anti-cancer therapeutics." (PMID 38424045, 2024). "Furthermore, MYC-driven cancer cells depend on various context-dependent RST mechanisms." (PMID 39456601, 2024). "However, whether PDPK1 and WDR5 contribute to similar mitotic gene regulation in MYC-overexpressing cancers remains unclear." (PMID 38605297, 2024). "Hence, XPO1 is essential and MYC synthetic lethal in vitro in multiple types of MYC-driven cancer." (PMID 38302473, 2024). "We hypothesize that those MYC amplification cancer cells may undergo RB1 loss in mRNA or protein level without RB1 deletion." (PMID 38424044, 2024). "Moreover, emerging evidences indicate that MYC can act as a key regulator of cancer stem cells." (PMID 38166947, 2024). "Since MYC-driven cancer cells are vulnerable to inhibition of Aurora A and ATR which suppress increases in R-loop, TRC, and DNA damage, MYC activation may not only cause transcription-associated RS but also elevate the tolerability for survival and growth under this stress." (PMID 39456601, 2024). "Moreover, the insights gained from this study may have broader implications for addressing resistance in other MYC-driven cancer types." (PMID 38326887, 2024). "Furthermore, to ask whether SE-relevant genomic regions are intact upon radiation exposure, we quantified the amounts of nascent RNA transcript from MYC, a bona fide oncogene driven by SE in several types of cancers." (PMID 38874522, 2024). "However, its multiple roles in different aspects of cellular biology suggest that it may also play a role in many additional diseases, and other publications are indeed linking MYC to pathologies beyond cancer." (PMID 38510176, 2024). "Thus, upregulation of TERT might promote the clonal expansion of cancer cells by activating the MYC pathway, in addition to maintaining telomere function." (PMID 39020172, 2024). "The acquisition of super-enhancers that regulate the expression of genes involved in cancer initiation and progression contributes to tumorigenesis Super-enhancers have been found near the MYC gene, resulting in altered chromatin structures and high production of MYC mRNA and protein." (PMID 39501082, 2024). "Therefore, targeting downstream targets of Myc could be more effective in treating cancer patients with MYC gene amplification." (PMID 38638876, 2024). "Thus, it can be reasonably expected that a clinical-grade DHODH inhibitor combined with venetoclax might improve outcomes for HGBCL patients, as well as other cancers with high expression of MYC and BCL2 or MYC and MCL-1." (PMID 38918775, 2024). "Innovations involving augmented co-factors, combining antitumor agents and super inhibitors, such as THZ1 and JQ1 (direct MYC inhibitors) with self-immune response, to modulate multiple signaling pathways simultaneously, may prevent cancer recurrence and progression to MDR in the long-term." (PMID 37450923, 2024). "However, the exact mechanism of JMJD6 in MYC-driven cancers remains elusive." (PMID 38488852, 2024). "MYC is also a master regulator of cancer metabolism involved in ribosomal and mitochondrial biogenesis, glucose and glutamine metabolism, and lipid synthesis, leading to the acquisition of bioenergetic substrates enabling the cancer cell to grow and proliferate." (PMID 38488852, 2024).
cancer (continued). "In addition, future work has to determine if this tumor-dominant expression of PVT1 is a common phenomenon of MYC-copy-increased cancers as that might pave the way for the development of “off-the-shelf” vaccines against many cancers." (PMID 38731892, 2024). "Thus, double-gated regulation of LHS by MYC/EGLN and HIF-1α has potential to elevate intracellular ROS levels, which is a prerequisite for triggering ferroptosis and provides an alternative cell death pathway to kill apoptosis and autophagy resistant MYC-driven cancer cells." (PMID 37450923, 2024). "Hence, co-treatment of patients with MYC-induced cancer using conventional therapeutic approaches in conjunction with herbal medicine may become a future trend in cancer therapeutics." (PMID 37450923, 2024). "Abnormal changes in ribosomes may drive cancer pathogenesis, and MYC is a master regulator." (PMID 38918775, 2024). "Thus, altered nuclear export of RNAs is a dependency of MYC-driven cancers." (PMID 38302473, 2024). "In addition, followingstability experiments and further work that showed that some of thedescribed leads directly bind MYC, and effectively enter the cells,we proceeded to in vivo pharmacokinetic studies in mice, which providedfurther evidence that efficacy in cancer models is possible." (PMID 39698270, 2024). "While G4s have been predominantly associated with the promoters of oncogenes such as MYC, KIT or KRAS, where their stabilization is associated with suppressed oncogene expression, we explored their potential role in exonic regions and the associated impact on genomic instability in cancer patients." (PMID 38407356, 2024). "Moreover, the introduction of promiscuous G4 stabilizing molecules, such as CX-5461, in combination with PPRHs could further enhance KRAS and MYC silencing in dependent cancers." (PMID 39457457, 2024). "Interestingly, several of these proteins are also known to be important in MYC-driven cancers like ribosome components (such as Rps8), multiple subunits of the eukaryotic translation initiation factor 3 complex, and proteins important for MYC-induced autophagy (such as Atg3)." (PMID 38302473, 2024). "Given that a major hurdle in cancer treatment is the need to pinpoint the subset(s) of patients who might benefit from any emerging targeted therapy, we propose that MYC(N) hyperactivation might become a useful predictive biomarker in NUDT1-based treatment regimen." (PMID 38493213, 2024). "Hence, targeted intervention to modulate c-MYC expression might be an effective therapeutic approach for cancer patients." (PMID 38622518, 2024). "Additionally, oncogenic signaling and cancer hallmarks were further aggravated in high-risk patients, such as epithelial-mesenchymal transition (EMT), glycolysis, angiogenesis, DNA repair, TGFβ signaling, mTORC1 signaling, MYC and E2F targets." (PMID 38886346, 2024). "Moreover, NCAPG2 could promote PCa malignancy and drive cancer stemness through a previously unreported STAT3/c-MYC signaling-dependent mechanism, which provides a new direction for targeted PCa therapy." (PMID 38166947, 2024). "Besides the dynamic abundance of MYC effecting global transcriptional changes involved in oncometabolism and oncoimmunology, MYC can modulate gene targets that induce metabolic changes influencing cancer immunity and possess dual roles in cancer development." (PMID 38390324, 2024). "However, MYC itself has been one of the most challenging targets for cancer treatment." (PMID 38200580, 2024). "However, the exact mechanisms that govern the role and dynamics of MYC in initiating cancer cells remain unclear." (PMID 39615685, 2024). "Thus, by examining the interactions between MYC and pyroptosis, it may be possible to design novel cancer treatments, particularly for apoptosis-resistant cancers that often escape apoptosis by overexpressing anti-apoptotic proteins." (PMID 37450923, 2024).
cancer (continued). "Based on our findings, we hypothesized that RUNX1T1 also plays a role in other MYC-driven cancers." (PMID 38992040, 2024). "However, when MYC is overexpressed, it triggers a cascade of cellular stress responses, leading to the transformation of normal cells into cancerous ones, thereby driving cancer progression and potentially affecting the efficacy of cancer treatments." (PMID 38638876, 2024). "Therefore, down-regulating the transcription of the oncogene c-MYC may be a feasible cancer treatment strategy." (PMID 38240704, 2024). "Thus, both HIF1A and MYC are key therapeutic targets for cancer progression." (PMID 38390324, 2024). "Consequently, the authors propose that compound 12 could be further studied for the development of therapeutic agents targeting MYC-driven cancers." (PMID 37568727, 2023). "Notably, since CTDNEP1 mutations or deletions have also been identified in other cancers, CTDNEP1 might play a broader role in cancer formation serving as a molecular link regulating MYC activity and expression across different cancer types." (PMID 36765089, 2023). "Quantification of a mitochondrial gene panel confirmed that MYC restores the majority of mitochondrial genes in ATF1 deficient MDA-MB-231 and A549 cells, indicating that coordinated nuclear pluripotency and mitochondrial biogenesis are required for ATF1 dependent cancer stemness." (PMID 37463926, 2023). "The mechanism suggests that other cancer subtypes with high MYC activation could also be targeted." (PMID 37377612, 2023). "Interestingly, MYC is important to activate mitochondrial biogenesis in cancer and could promote the growth of LUAD cells by regulating the structure and function of mitochondria." (PMID 36982777, 2023). "Thus, MYC supports both the growth of cancer cells and their evasion of antitumor immunity." (PMID 36768931, 2023). "Thus, KRAS mutations appear to cause the overexpression of MYC and ARF6 proteins in cancer cells." (PMID 37158894, 2023). "Consequently, the downregulation of c-MYC has emerged as an enticing strategy for cancer treatment." (PMID 38275631, 2023). "MYC is a notorious oncogene, yet mitochondrial disease patients do not show increased cancer risk." (PMID 37731815, 2023). "RNA methyltransferase (RNMT) recruitment to the promoters of genes in the canonical Wnt/β-catenin signaling pathway promoted by MYC-mediated Ser 5 phosphorylation of RNA Polymerase II enhanced mRNA cap methylation and increased translational capacity and elevating protein expression in cancer cells." (PMID 37612540, 2023). "Notably, the observation that MIAT silencing decreases the expression of the oncogene c-MYC, which is often deregulated in many cancers and is considered ‘undruggable’, provides an exciting opportunity to explore the development of therapeutic materials targeting c-MYC." (PMID 37624039, 2023). "However, MYC is estimated to be overexpressed up to 70% in various human cancer types." (PMID 37570631, 2023). "Hence, the MYC protein can be considered as an ideal target for the cancer treatment." (PMID 36830089, 2023). "However, targeting c-MYC has become an essential step in molecular therapy in human cancers." (PMID 38003498, 2023). "Importantly, pharmacological inhibition of ST6GALNAC4 to block Siglec ligand biosynthesis may be an effective immune therapy strategy for cancers with elevated MYC activity." (PMID 36897988, 2023). "Our findings that Omomyc is able to modulate the MYC/MAX ratio in cancer cells suggest that Omomyc may affect MYC/MAX-dependent transcription by binding to chromatin as homodimers that largely displace MYC from DNA and can compromise DNA binding of MAX/MAX complexes as well." (PMID 36830948, 2023).